CCDC22 (CCC complex scaffolding subunit CCDC22)
Description:
Component of the commander complex that is essential for endosomal recycling of transmembrane cargos; the Commander complex is composed of composed of the CCC subcomplex and the retriever subcomplex. Component of the CCC complex, which is involved in the regulation of endosomal recycling of surface proteins, including integrins, signaling receptor and channels. Involved in regulation of NF-kappa-B signaling. Promotes ubiquitination of I-kappa-B-kinase subunit IKBKB and its subsequent proteasomal degradation leading to NF-kappa-B activation; the function may involve association with COMMD8 and a CUL1-dependent E3 ubiquitin ligase complex. May down-regulate NF-kappa-B activity via association with COMMD1 and involving a CUL2-dependent E3 ubiquitin ligase complex. Regulates the cellular localization of COMM domain-containing proteins, such as COMMD1 and COMMD10. Component of the CCC complex, which is involved in the regulation of endosomal recycling of surface proteins, including integrins, signaling receptor and channels. The CCC complex associates with SNX17, retriever and WASH complexes to prevent lysosomal degradation and promote cell surface recycling of numerous cargos such as integrins ITGA5:ITGB1. Plays a role in copper ion homeostasis. Involved in copper-dependent ATP7A trafficking between the trans-Golgi network and vesicles in the cell periphery; the function is proposed to depend on its association within the CCC complex and cooperation with the WASH complex on early endosomes. (Microbial infection) The CCC complex, in collaboration with the heterotrimeric retriever complex, mediates the exit of human papillomavirus to the cell surface.
Synonyms: CXorf37; JM1; RTSC2
Tractability: PROTAC: ubiquitination databases record sites on it; its protein half-life has been measured.
Gene: Protein-coding gene on chromosome X (49,235,444 to 49,250,526, forward strand). Ensembl gene ENSG00000101997.
Subcellular location: Endosome; Cytoplasm, cytoskeleton, microtubule organizing center, centrosome
Subcellular location (Human Protein Atlas): Endoplasmic reticulum; Vesicles
Pathways (Reactome):
Metabolism of proteins: Neddylation
Gene Ontology:
Molecular function: cullin family protein binding; protein binding
Biological process: endocytic recycling; Golgi to plasma membrane transport; intracellular copper ion homeostasis; negative regulation of canonical NF-kappaB signal transduction; positive regulation of canonical NF-kappaB signal transduction; positive regulation of ubiquitin-dependent protein catabolic process
Cellular component: centrosome; protein-containing complex; cytosol; endoplasmic reticulum membrane; endosome membrane; nucleoplasm; endosome
Gene-disease validity (ClinGen):
ClinGen rates the evidence that CCDC22 causes each of these diseases.
Ritscher-Schinzel syndrome 2 (X-linked): Moderate.
Homologues: Orthologues: chimpanzee CCDC22 (99% identical), macaque CCDC22 (98% identical), pig CCDC22 (93% identical), dog CCDC22 (92% identical), mouse Ccdc22 (88% identical), rat Ccdc22 (88% identical), guinea pig CCDC22 (83% identical), rabbit CCDC22 (67% identical), zebrafish ccdc22 (56% identical), tropical clawed frog ccdc22 (55% identical), Drosophila melanogaster CG9951 (26% identical), Caenorhabditis elegans R08E3.3 (18% identical).
Diseases named in the same sentence as CCDC22 in open-access papers:
CCDC22 is named in the same sentence as 19 diseases in open-access papers, as found by Europe PMC text mining. Sharing a sentence is not in itself a finding about the gene and the disease. The quoted sentences say what the papers report.
X-linked intellectual disability (6 papers, 2016 to 2025). An X-linked intellectual deficiency in which not enough information is known, reported or published to indicate whether a gene causes non-syndromic or syndromic presentations. "Missense mutations and subsequent downregulation of CCDC22 are potential mechanisms underlying X-linked intellectual disability and Ritscher-Schinzel syndrome in humans." (PMID 40310674, 2025). "Analysis of a cohort of X-linked intellectual disability (XLID) patients identified multiple mutations in the N-terminal half of CCDC22." (PMID 29778605, 2018). "We find that patients with X-linked intellectual disability caused by mutations in CCDC22 are hypercholesterolaemic, and that COMMD1-deficient dogs and liver-specific Commd1 knockout mice have elevated plasma LDL cholesterol levels." (PMID 26965651, 2016). "In this same study, we reported that X-linked intellectual disability (XLID) patients carrying a mutation in CCDC22 (c.49A>p.T17A) also have aberrant copper homeostasis, as serum copper and serum ceruloplasmin levels are increased in these patients." (PMID 26965651, 2016). "Among these genes, PLP2, CCDC22, and SYP mutations were associated with X-linked intellectual disability." (PMID 34659328, 2021).
Ritscher-Schinzel syndrome (3 papers, 2023 to 2025). "For example, and unsurprisingly given how the syndrome is defined, Ritscher-Schinzel syndrome genes CCDC22 and VPS35L shared highly similar phenotypes." (PMID 39282277, 2024). "Ritscher-Schinzel syndrome is a developmental disorder characterized by abnormal craniofacial, cerebellar, and cardiovascular malformations, classically associated with WASHC5 and CCDC22 but more recently with VPS35L and DPYSL5 being implicated as well." (PMID 39282277, 2024). "The Retriever subunit VPS35L is the third responsible gene for Ritscher-Schinzel syndrome (RSS) after WASHC5 and CCDC22." (PMID 36113987, 2023).
hypercholesterolaemia (2 papers, 2016 to 2023).
cervical cancer (1 paper, 2025). A primary or metastatic malignant neoplasm involving the cervix. "Our results suggest the possible roles of CCDC22 and PDHA1 in the regulation of cuproptosis in cervical cancer, which deserves further investigation." (PMID 41142609, 2025). "Using this signature, the patients were divided into Cluster A and Cluster B. Compared with Cluster A, most cuproptosis genes (such as CCDC22, PDHA1, ARF1, and AQP1) in Cluster B were highly expressed, resulting in a better prognosis for patients with cervical cancer." (PMID 41142609, 2025).
ovarian carcinoma (1 paper, 2025). A malignant neoplasm originating from the surface ovarian epithelium. "The co-IP of CCDC22 with MMP3 in cisplatin-resistant OVCAR3CIS cells highlights a potentially significant interaction that may contribute to cisplatin resistance in ovarian cancer cells." (PMID 40362252, 2025).
Ritscher-Schinzel syndrome-2 (1 paper, 2019). "It is also noteworthy that missense mutations in CCDC22 are associated with Ritscher-Schinzel syndrome-2 an X-linked recessive syndromic form of ID associated with posterior fossa defects, cardiac malformations, and minor abnormalities of the face and distal extremities." (PMID 30914922, 2019).
cancer (2 papers, 2021 to 2025). A tumor composed of atypical neoplastic, often pleomorphic cells that invade other tissues. "ACE2, RAB7A, CCDC22, ATP6AP1, NPC1, and PIK3C3 exhibited a positive relationship with sensitivity of 18 anti-cancer drugs (P < 0.01)." (PMID 35082790, 2021). "Furthermore, 62.5% of SARS-CoV-2-required genes containing ACE2, TMPRSS2, ATP6AP1, ATP6V1A, and CCDC22 exhibited a significant upregulation in UCEC relative to normal tissue, while only PIK3C3 showed an obvious downregulation in this cancer." (PMID 35082790, 2021).
infection (2 papers, 2019 to 2022). The state of being infected such as from the introduction of a foreign agent such as serum, vaccine, antigenic substance or organism. "Many of the hits were associated with intracellular transport or endosome activity, including VPS29, the CCDC22/CCDC93/COMMD3 (CCC) complex, and the WDR81/91 complex, suggesting a requirement for these functions in HCoV-OC43 infection." (PMID 35229640, 2022).
hematologic cancer (1 paper, 2021). "The high expression levels of RAB7A, PIK3C3, ATP6AP1, ATP6V1A, CCDC22, and NPC1 were significantly associated with lower tumor purity of patients with hematologic cancer LAML, while TMPRSS2, PIK3C3, ATP6AP1, and ATP6V1A expressions were obviously correlated with higher tumor purity of KICH patients." (PMID 35082790, 2021).
CCDC22 also shares sentences with these, for which no sentence is quoted: neurodevelopmental disorder (2 papers); epilepsy (1); genetic disorders (1); hypercholesterolemia (1); leukemia (1); metabolic disorders (1); myopia (1); psoriasis (1); tumor (1); X-linked disease (1).